RABL3 (RAB, member of RAS oncogene family like 3)
Description:
Small GTPase required for KRAS signaling regulation and modulation of cell proliferation. Regulator of KRAS prenylation, and probably prenylation of other small GTPases. Required for lymphocyte development and function (By similarity). Not required for myeloid cell development (By similarity). Interacts with Rab11 to promote ciliary vesicle formation at the mother centriole, thereby regulating early ciliogenesis. The GTP-binding capacity of RABL3 is essential for ciliogenesis.
Synonyms: MGC23920; PNCA5
Tractability: PROTAC: ubiquitination databases record sites on it; its protein half-life has been measured; a small molecule that binds it is known.
Gene: Protein-coding gene on chromosome 3 (120,684,938 to 120,742,993, reverse strand). Ensembl gene ENSG00000144840.
Subcellular location: Cytoplasm, cytoskeleton, microtubule organizing center, centrosome; Golgi apparatus
Subcellular location (Human Protein Atlas): Endoplasmic reticulum
Gene Ontology:
Molecular function: G protein activity; protein binding; GTP binding; GTPase activity; protein homodimerization activity
Biological process: positive regulation of cilium assembly; regulation of protein lipidation; regulation of Ras protein signal transduction; B cell differentiation; natural killer cell differentiation; protein stabilization; T cell differentiation in thymus
Cellular component: Golgi apparatus; centrosome
Genetic constraint (gnomAD): Loss-of-function variants: 4 observed, 6.38 expected, observed/expected ratio (o/e) 0.63, 90% interval 0.31 to 1.41. That is too few expected variants to judge how well the gene tolerates losing a copy. Missense variants: 76 observed, 82.93 expected, observed/expected ratio (o/e) 0.92, 90% interval 0.76 to 1.11. Synonymous variants: 26 observed, 31.25 expected, observed/expected ratio (o/e) 0.83, 90% interval 0.61 to 1.15.
Homologues: Orthologues: chimpanzee RABL3 (100% identical), macaque RABL3 (99% identical), pig RABL3 (97% identical), guinea pig RABL3 (94% identical), mouse Rabl3 (92% identical), tropical clawed frog rabl3 (86% identical), zebrafish rabl3 (83% identical), rat Rabl3 (82% identical).
Diseases named in the same sentence as RABL3 in open-access papers:
RABL3 is named in the same sentence as 12 diseases in open-access papers, as found by Europe PMC text mining. Sharing a sentence is not in itself a finding about the gene and the disease. The quoted sentences say what the papers report.
gastric cancer (3 papers, 2021 to 2023). A primary or metastatic malignant neoplasm involving the stomach. "Inhibition of the circCOL1A1/miR-145/RABL3 pathway effectively attenuates the proliferation, migration, and invasion of gastric cancer." (PMID 34631898, 2021). "Inhibition of circCOL1A1/miR-145/RABL3 could effectively suppress gastric cancer cell proliferation, migration, and invasion." (PMID 34631898, 2021). "The expression levels of RABL3 were also tested in gastric cancer tissues." (PMID 34631898, 2021). "We confirmed the existence of circCOL1A1/miR-145/RABL3 in gastric cancer tissue." (PMID 34631898, 2021). "Given the previous results, we considered that the circCOL1A1/miR-145/RABL3 axis might be involved in the progress of gastric cancer." (PMID 34631898, 2021). "Whether circCOL1A1 promotes malignant progression of gastric cancer through miR-145/RABL3 axis still needs to be confirmed." (PMID 34631898, 2021). "The results show that miR-145 acts as a regulator of RABL3 in gastric cancer." (PMID 34631898, 2021). "A recent study has reported that circCOL1A1, also known as hsa_circ_0044556, is increased in gastric cancer (GC), and promotes GC growth and metastasis via miR-145/RABL3 axis." (PMID 37940881, 2023). "miR-145/RABL3 might be a possible target for gastric cancer." (PMID 34631898, 2021).
pancreatic cancer (3 papers, 2021 to 2022). "In addition, WES in a family affected by hereditary pancreatic cancer revealed a nonsense mutation in the gene encoding the small GTPase Rab-like protein 3 (RABL3), resulting in a truncated protein." (PMID 35178568, 2022). "These proteins consist of the N-terminal portions of RabL3 or Rab22a, and exhibit enhanced binding to SmgGDS-607 and SmgGDS-558 in pancreatic cancer and osteosarcoma, respectively, and are also detected in breast cancer." (PMID 34222337, 2021). "The abnormal RabL3 protein that occurs in familial pancreatic cancer is a truncated protein consisting of the first 1–36 amino acids of RabL3, designated RabL31–36." (PMID 34222337, 2021).
non-small cell lung carcinoma (2 papers, 2019 to 2021). A group of at least three distinct histological types of lung cancer, including non-small cell squamous cell carcinoma, adenocarcinoma, and large cell carcinoma. "High level of RABL3 is related to the poor survival of non-small-cell lung cancer patients." (PMID 34631898, 2021). "Autophagy mediated by MAPK8/9/10 could be repressed by Rabl3, leading to poor survival of non-small cell lung cancer." (PMID 31508368, 2019).
hepatocellular carcinoma (1 paper, 2022). A malignant tumor that arises from hepatocytes. "On the other hand, it acts as tumor suppressor miRNA in metastatic cancer and in an advanced clinical stage of hepatocellular carcinoma by targeting ARHGAP18, Rabl3 and snail which are up-regulated and implicated in migration and metastasis of this type of cancer cells." (PMID 36158686, 2022).
oral squamous cell carcinoma (1 paper, 2023). "Knockdown of RABL3, which belongs to the Rab subfamily, inhibits the proliferation and invasion of oral squamous cell carcinoma through deactivating the FAK/AKT pathway." (PMID 36760469, 2023).
cancer (3 papers, 2010 to 2025). A tumor composed of atypical neoplastic, often pleomorphic cells that invade other tissues. "miR-153 has been reported to inhibit the proliferation and invasion of cancer cells through various targets, including Rabl3, ARHGAP18, SNAI1, and Wnt/β-catenin." (PMID 39866238, 2025).
tumor (2 papers, 2013 to 2021). "We also examined the expression of circCOL1A1/miR-145/RABL3 in nude mouse tumor tissue and patient tissues." (PMID 34631898, 2021). "Moreover, small GTPase subfamily Rab-like 3 (Rabl3) and actin-binding protein Myotilin, promote motility, tumor cell survival." (PMID 23950931, 2013).
RABL3 also shares sentences with these, for which no sentence is quoted: breast carcinoma (1 paper); infection (1); lung carcinoma (1); Obesity (1); RASopathy (1).